INS (insulin)
Diseases named in the same sentence as INS in open-access papers (continued):
Sharing a sentence is not in itself a finding about the gene and the disease.
Glucose intolerance (continued). "Using the same STZ-induced diabetic model and the same drug treatment paradigm, we found that [Ser4, Ile8]-OXT treatment significantly prevented STZ-induced glucose intolerance, and this effect was accounted for by the improvement on insulin secretion rather than body weight." (PMID 23700406, 2013). "The value in gaining and understanding of the mechanisms that govern glucose and insulin responses in healthy carnivores is the insight provided into the possible pathologic mechanisms that produce similar changes leading to glucose intolerance in non-carnivore species." (PMID 24348462, 2013). "Altered islet architecture and abnormal pattern of islet size distribution in transgenic mice do not affect islet secretory function in vitro and, therefore, does not play a significant role in glucose intolerance and impaired insulin secretion exhibited by p-KO mice in vivo." (PMID 23923060, 2013). "However, as insulin-stimulated glucose uptake in isolated EDL and soleus muscles was maintained in HFD fed mice our findings suggest that the glucose intolerance was not due to the presence of skeletal muscle insulin resistance." (PMID 23951235, 2013). "However, blood pressure was not reported in those studies, thus rendering impossible any interpretation of the effects on insulin resistance (with or without glucose intolerance) on blood pressure." (PMID 23586038, 2013). "However, despite this glucose intolerance, the RenTgMK mice maintained low fasting insulinemia and normal insulin sensitivity, as indicated by normal steady-state glucose infusion during the hyperinsulinemic, euglycemic clamp studies." (PMID 23308073, 2012). "It is important to note that although insulin is a potent activator of mTOR through Akt regulatory pathways, mTOR may have a negative feedback loop and led to glucose intolerance through inhibition of the insulin receptor substrate 1 (IRS1)." (PMID 22545721, 2012). "In addition, both increased GLP-1 and insulin concentrations were not sufficient to counteract glucose intolerance." (PMID 21698161, 2011). "Therefore, we hypothesize in the BEDIP-FUS study that each degree of gestational glucose intolerance based on the antenatal GCT and OGTT with the 2013 WHO criteria predicts distinct postpartum trajectories of weight, β-cell function, insulin sensitivity and glycaemia in both women and offspring." (PMID 36769669, 2023). "Thus, in the non-pregnant state, dysregulated skeletal muscle insulin signalling in the α/+ mice may be related to their glucose intolerance." (PMID 35846351, 2022). "Whether this response is due to decreased cardiac and skeletal muscle uptake of glucose or impaired insulin signaling is not clear, but glucose intolerance in mice fed with the KD for 6 weeks and decreased insulin sensitivity in rats fed with the KD for 8 weeks has been reported." (PMID 34207054, 2021). "Furthermore, there were no changes observed in fasting plasma insulin levels, suggesting that the lack of glucose intolerance in adi-KO mice may be due to increased insulin sensitivity." (PMID 33397965, 2021). "However, the Afmid mouse also has a thymidine kinase promoter deleted and a glucose intolerance phenotype with reduced insulin secretion and therefore is not a clean model from which a direct inference of an effect on kynurenine metabolism on renal function can be drawn." (PMID 30760699, 2019). "Moreover, treatment of crocin resulted in a amelioration of general metabolic disorder, as evidenced by decreased fasting blood glucose, reduced serum levels of insulin, triglyceride, total cholesterol, and non-esterified fatty acid, and improved glucose intolerance." (PMID 30621686, 2019). "Second, the presence of subjects with glucose intolerance could not be ruled out in the population studied, however, similar to our observations, previous studies have found that IFG is mainly associated with derangements in hepatic insulin sensitivity." (PMID 27843495, 2016).
Glucose intolerance (continued). "However, although the muscle is the primary tissue that responses to insulin, there are some indications that fat tissue expression of GLUT4 might actually be more important for the development of glucose intolerance and decreased GLUT4 expression would be an indication of insulin-resistant state." (PMID 23457588, 2013). "The absence of hepatocyte PI3Kα reduced maximal insulin-induced PI3K activity and signaling, promoted glucose intolerance in lean mice and significantly regulated liver gene expression, including insulin-sensitive genes, in ad libitum feeding." (PMID 40228209, 2025). "Targeted deletion of vascular NGF or β-cell TrkA impairs GSIS and provokes glucose intolerance, whereas exogenous NGF enhances GSIS in human islets without elevating basal insulin output." (PMID 41471293, 2025). "Neither Tie2e‐Cre;TERTfl/fl nor LysM‐Cre;TERTfl/fl males displayed glucose intolerance after a CR and subsequent HFD feeding course; in fact, KO mice in both models were more insulin‐sensitive." (PMID 39932851, 2025). "Coupled with the fact that fasting insulin and glucose levels were not significantly altered in CBD-exposed males, we postulated that the glucose intolerance is likely not due to deficits in endocrine pancreas development." (PMID 37855335, 2024). "Under HFFD conditions, GTT analysis of WT mice again showed glucose intolerance, but KO mice were glucose tolerant (left) and the ITT of KO mice showed significant insulin sensitivity under HFFD conditions, but not that of WT mice (right)." (PMID 35123128, 2022). "In the current study, serum IGF-I levels were significantly higher in individuals with glucose intolerance and were correlated with FPG and HbA1c, but not with serum C-peptide, insulin, and HOMA-IR." (PMID 34239560, 2021). "We reviewed the literature on glucose and insulin responses to oral glucose in GIP and GLP-1 receptor KO mice and found that glucose intolerance is not as robustly demonstrated as is generally assumed." (PMID 34122340, 2021). "Blocking the endogenous CRHR2 agonist during gestation induces a mild glucose intolerance rather than overt gestational diabetes suggesting that UCN2 may act in concert with other placental signals to fine-tune the compensatory β-cell adaptations to maternal insulin resistance during pregnancy." (PMID 32106091, 2020). "Insulin levels during an oral glucose tolerance test (OGTT) were similar in Pax8 +/- mice, suggesting that glucose intolerance in these animals is not due to major defects in glucose-stimulated insulin secretion." (PMID 31518338, 2019). "Although MGO administration did not alter body weight, it aggravated glucose intolerance (AUC0–120) and increased fasting plasma glucose and insulin." (PMID 31388341, 2019). "We assume that the modest effect of coffee on insulin level was not enough to alter a composite index such as the Matsuda in 17-week-old ZDF rats with advanced beta-cell dysfunction and glucose intolerance." (PMID 31484373, 2019). "VDD in low fat diet did not significantly affect glucose tolerance and insulin sensitivity, but aggravated the HFD-induced glucose intolerance." (PMID 27895587, 2016). "The discrepant finding of whole-body glucose intolerance in the absence of impaired, albeit maximal, insulin signaling and glucose uptake in soleus and EDL in OVX sed rats prompted us to measure markers of insulin signaling in other insulin-sensitive tissues." (PMID 26603453, 2015). "Regardless of the genotype, mice on an HFD showed glucose intolerance, and Gcggfp/gfp mice on HFD exhibited impaired insulin secretion whereas Gcggfp/+ mice on HFD exhibited increased insulin secretion." (PMID 26378455, 2015). "Despite restoration of normal resting glucose and insulin levels, SOX17 expression did not reverse the glucose intolerance of Pdx1tTA/+ mice." (PMID 25144761, 2014).
Glucose intolerance (continued). "Collectively, these results suggest that glucose intolerance of SERT mutant mice is more likely due to reduced response to insulin, rather than reduced pancreatic insulin secretion." (PMID 22412882, 2012). "Neither genotype showed glucose intolerance, but D2KO mice had significantly higher insulin levels during GTT independent of diet." (PMID 21698184, 2011). "Reduced insulin secretion capacity in CHD-fed 129S6, BALB/c and C3H mice relative to C57BL/6 and DBA/2 did not correlate with HFD-promoted glucose intolerance which develops more prominently in C57BL/6 and 129S6 mice." (PMID 18301746, 2008). "Thus, short-term αActRIIA/IIB treatment markedly enhanced muscle insulin-stimulated glucose uptake independent of AKT-TBC1D4 muscle insulin signaling but paradoxically elevated blood glucose and induced glucose intolerance." (PMID 41022302, 2025). "Experimental models reinforce this link: mice lacking insulin and insulin-like growth factor 1 (IGF-1) receptors exhibit both glucose intolerance and cognitive impairment, and AD mice crossbred with diabetic strains display lower insulin levels and more rapid cognitive decline." (PMID 40948809, 2025). "TCDD-exposed males were hypoglycemic or normoglycemic during glucose tolerance tests (GTTs) and had increased insulin sensitivity during an insulin tolerance test (ITT), whereas TCDD-exposed females showed transient glucose intolerance and no change in insulin sensitivity compared to controls." (PMID 35156417, 2022). "Mice with anti-miR-185-5p LNA injection also exhibited increased hepatic gluconeogenesis and glucose intolerance as determined by GTT and PTT, respectively, without changes in insulin sensitivity as determined by ITT; the area under the curve (AUC) of glycemia was also calculated." (PMID 34335967, 2021). "Moreover, at early postpartum, the non-responders exhibited higher FPG, fasting insulin, HOMA-IR, and higher proportion of glucose intolerance compared to responders." (PMID 34620173, 2021). "Interestingly, glucose intolerance was improved in CCDC3 TG mice, although their insulin sensitivity was not altered in comparison with that of control mice." (PMID 28827783, 2017). "Unlike insulin, naringin improved neither FBG nor glucose intolerance in STZ-treated rats." (PMID 27073901, 2016). "Our results suggest that although some reduction of hepatic insulin sensitivity may have been induced by IDFP, this is likely not sufficient to have produced the profound glucose intolerance that was observed." (PMID 22073164, 2011). "In addition, F1-BPA100 mice presented milder glucose intolerance than F1-BPA10 mice but normal insulin sensitivity and plasma insulin levels that were not statistically different from controls." (PMID 20488778, 2010). "Importantly, no impairment in insulin secretion was evident in islets isolated from RT-SAKO mice that could explain the impaired in vivo GSIS and glucose intolerance in these mice." (PMID 38280449, 2024). "It should be noted that exacerbated glucose intolerance is observed only in HFD-fed, but not normal diet-fed, Becn1F121A mice, suggesting that the impairment in insulin storage is more apparent only when the animals become pre-diabetic and the peripheral demand for insulin is increased." (PMID 29898399, 2018). "Although k2, the rate constant for flux from glucose to effective glucose for insulin secretion, differed significantly among the three groups, it decreased in the rank order T2DM > NGT > IGT, indicating that k2 does not represent progression of glucose intolerance." (PMID 26623647, 2015).
Hypertension (2,443 papers, 2002 to 2026). The presence of chronic increased pressure in the systemic arterial system. "Specifically, after adjusting for sex, age, smoking, alcohol consumption, hypertension, and BMI (Model 4), each unit increase in alanine level was associated with a 31% higher likelihood of requiring insulin therapy (OR = 1.31, 95% CI: 1.24–1.38, p < 0.001)." (PMID 41531546, 2026). "Hypertension and use of insulin were associated with a higher risk of problems in mobility, selfcare, and usual activities." (PMID 41908907, 2026). "For example, elegant studies evaluating insulin signaling have not only shed light on its role in glucose metabolism but also its broader impact on cardiovascular health, including hypertension, atherosclerosis, and other CVD risk factors." (PMID 40403107, 2025). "Cellulose has been shown to inhibit starch digestion by binding to α-amylase, reducing glucose absorption, enhancing insulin sensitivity, and, as a result, lowering the risk of hypertension." (PMID 41154549, 2025). "Studies show that hypertension, abdominal obesity, and elevated HbA1c levels are associated with reduced insulin sensitivity, which in turn increases the risk of developing MetS." (PMID 41171818, 2025). "In the 20-year CARDIA study, participants in the highest insulin quartile had an 85% greater risk of developing hypertension (1.85; 95% CI: 1.42–2.40) compared with those in the lowest quartile." (PMID 41463109, 2025). "Lower 25(OH)D levels were associated with significantly older age, longer duration of hypertension, greater fasting plasma glucose and insulin, HOMA index, and plasma PTH." (PMID 39940336, 2025). "Obesity is an important cause of various cardiovascular diseases, bringing about hypertension, cardiac morphological changes, and insulin resistance; it also increases oxidative stress and inflammation in the heart." (PMID 40362616, 2025). "Age, male, BMI SBP, hypertension, use of insulin and DPP-4i, and prior CVD and DR, were associated with increased CKD risk." (PMID 40098113, 2025). "Lower 25(OH)D levels were associated with older age (p < 0.001), longer duration of hypertension (p = 0.019), higher fasting plasma glucose (p = 0.037), and insulin (p = 0.044), Homeostatic Model Assessment (HOMA) index (p = 0.044), and PTH (p < 0.001)." (PMID 39940336, 2025). "Of special interest is the Enterobacter hallii group, whose abundance has been associated with age, hypertension, inflammation, and insulin sensitivity." (PMID 40964671, 2025). "Compared with essential hypertension, primary aldosteronism, a disease characterized by excessive plasma aldosterone concentrations, is associated with reduced insulin sensitivity and elevated β-cell function." (PMID 40296149, 2025). "Mediation analyses indicated that HbA1c, insulin, and hypertension indirectly mediated the associations between TyG, TyG-WHtR and all-cause mortality, CVD mortality, total CVD, CHF, CHD and angina pectoris." (PMID 39026233, 2024). "On the other hand, chronic low-dose treatment of Ang-II resulted in the development of hypertension that was associated with AT1aR-dependent enhanced insulin signaling." (PMID 39456189, 2024). "This suggests that fasting insulin (BMI adjusted) is the critical entity that underlies the positive association of IR and hypertension." (PMID 38485964, 2024). "Studies found the overactive sympathetic system in insulin-resistant patients, is another causative factor in insulin-mediated hypertension." (PMID 38441007, 2024). "Reduced muscle mass and intramuscular fat infiltration cause a decrease in insulin-responsive target tissue, resulting in insulin resistance; consequently, arterial stiffness increases, which indicates the onset of hypertension." (PMID 39540100, 2024). "Although IR serves as a possible tool to assess the potential risk of hypertension, serum insulin levels are largely affected by the fasting status of individuals and thus not widely applied to the routine health examinations." (PMID 38566188, 2024).
Hypertension (continued). "Insulin use, sulfonylurea and presence of diseases of the circulatory system excluding hypertension were risk factors." (PMID 38536830, 2024). "The increase in the risk of developing hypertension and hyperlipidaemia is associated with an increased CV risk through adverse effects on lipid concentrations, insulin resistance, and other cardiometabolic processes." (PMID 39497061, 2024). "The phenotypes with more associations were the age of hypertension onset (n = 244), BMI (n = 88), insulin doses (n = 74), and cholesterol levels (n = 67)." (PMID 39337639, 2024). "Multivariable MR revealed that fasting insulin adjusted for BMI was associated with hypertension after adjustment for other components of IR." (PMID 38485964, 2024). "Nevertheless, since U-shaped associations between alcohol consumption and insulin levels have been demonstrated, heavy alcohol intake has also been related to elevated levels of fasting glucose and triglycerides, as well as hypertension and central obesity." (PMID 38398871, 2024). "Patients who are prescribed insulin are likely to have multiple comorbidities such as hypertension, nephropathy, and CVD, which are also risk factors for DR." (PMID 38298309, 2024). "They reported that the higher the fasting insulin level, the higher the risk for hypertension and IHD." (PMID 39347227, 2024). "Our study also demonstrated that HbA1c, insulin, and hypertension partially mediate the association between TyG, TyG-WHtR, and CVD mortality, total-CVD, CHF, angina pectoris, and CHD." (PMID 39026233, 2024). "High levels of chemerin are associated with insulin over-production, hypertension, high glycosylated hemoglobin levels and endothelial damage." (PMID 36833129, 2023). "In pathological conditions, such as diabetes or hypertension, the concentration of ET-1 is increased because of the hyperglycaemia, acidosis and the presence of insulin, angiotensin II and proinflammatory cytokines, which causes sustained vasoconstriction." (PMID 36834836, 2023). "Despite the increased absolute AF incidence in the insulin group (as was seen in previous study), the accumulated hypertension burden had a similar impact on the risk of AF in patients with DM regardless of insulin usage." (PMID 36658574, 2023). "We further discovered that waist circumference, fasting insulin, glycated hemoglobin, and hypertension are also significantly associated with a higher risk of kidney stones." (PMID 37810889, 2023). "Since T2DM people is characterized with metabolic abnormalities associated with disorders of insulin action and insulin secretion, such as hypertension, elevated Triglycerides and low HDL-cholesterol, which have been identified as risk factors for T2DM4." (PMID 37524765, 2023). "Dysregulation of the hypothalamic-pituitary-adrenal (HPA) axis is linked to hypertension, increased heart rate, high levels of total and low-density lipoprotein cholesterol, as well as fasting insulin and glucose levels." (PMID 37999255, 2023). "A thoughtful meta-analysis has confirmed that in the general population, fasting insulin concentrations are independently linked to an increased risk of hypertension." (PMID 37875984, 2023). "Both EA and LA patterns were linked to increased odds of pre-hypertension/hypertension, elevated fasting insulin and elevated HOMA-IR." (PMID 36087338, 2023). "For example, both AD and T2DM are characterized by insulin and glucose tolerance, slowing down the metabolism, hypertension and, thus, one disease increases the risk of the another." (PMID 37895336, 2023). "In this regard, a study conducted in Los Angeles, California, found that in a Latin American population, risk factors such as male sex, insulin treatment, hypertension, and longer duration of DM were associated with the development of DR." (PMID 37892721, 2023).